VCAM1 (vascular cell adhesion molecule 1)
Diseases named in the same sentence as VCAM1 in open-access papers (continued):
Sharing a sentence is not in itself a finding about the gene and the disease.
diabetes (continued). "Thirdly, studies demonstrated that the oxidative stress induced by diabetes increased proinflammatory factors such as the level of TNF-α and IL-6 and raised inflammatory molecules like vascular cell adhesion molecule 1 (VCAM1)." (PMID 33456672, 2020). "The data showed that compared with the control group, the expression levels of CASP3, VCAM-1 and HGF were down-regulated in patients with syphilis and diabetes, while ALB, FN1, MMP9, IL8, CTGF, STAT3 and IGF1 were up-regulated." (PMID 32342229, 2020). "After 42-d treatment (72 d of total duration of diabetes), proinflammatory molecular VEGF-α, GFAP, and Vcam-1 protein expressions were detected by western blot method." (PMID 31396288, 2019). "VCAM-1 was improved in response to a low AGE diet, while OxLDL was increased following consumption of a high AGE diet in patients with diabetes." (PMID 26938557, 2016). "The results also indicate that diabetes can elicit the expression of adhesion molecules, including P-selectin, ICAM-1, and VCAM-1, which indirectly or directly promote development of ETD to induce CVD." (PMID 24499567, 2013). "Our clinical study with aorta pouch biopsy specimens from patients with diabetes and coronary artery atherosclerosis shows intense immunostaining for SREBP-1 and vascular cell adhesion molecule-1 (VCAM-1), a key inflammatory marker, in atherosclerotic plaques." (PMID 23825667, 2013). "After 12-week administration, we observed that RRP suppressed inflammatory gene expression and NF-κB activation and efficaciously reversed diabetes-induced elevation of ICAM-1 and VCAM-1 levels." (PMID 23662142, 2013). "To extend our in vitro findings on the role of Rho/ROCK in expression of MCP-1 and VCAM-1, we examined the effects of fasudil on serum sVCAM-1 and MCP-1 levels in patients with diabetes." (PMID 22694757, 2012). "In the development of the cardiovascular complications of diabetes, AGE-RAGE interaction upregulates the transcription factor NF-κB and its target genes, including the adhesion molecules (VCAM-1 and MCP-1)." (PMID 21350611, 2011). "In people with diabetes, plasma ADMA and VCAM-1 levels were positively correlated (r = 0.37, p = 0.003)." (PMID 19486510, 2009). "Additionally, other endothelial cell adhesion molecules, including E-selectin, vascular cell adhesion molecule-1 (VCAM-1), and intercellular adhesion molecule-1 (ICAM-1), were upregulated in diabetes, and their overexpression was positively correlated with OS." (PMID 39064844, 2024). "There was a significant positive association between vitamin C blood levels and lumbar spine BMD as well as a significant negative association between total adiponectin and VCAM-1 levels with that of vitamin C and lumbar BMD in patients with diabetes." (PMID 36235544, 2022). "In contrast to the heart, diabetes did not affect the numbers of ICAM‐1+ or VCAM‐1+ blood vessels in the brain." (PMID 35488737, 2022). "Differentially regulated genes not overlapping with ERCB data also reflected diabetes-associated changes, such as extracellular matrix (ANGPTL4, TNN, DPT, COL9A2) or gestational diabetes (LAT2, HP, CXCL10, CD86, CD68, REN, SLC2A3, VCAM1)." (PMID 33923831, 2021). "VCAM-1 is significantly more abundant in the urinary proteome of T2D patients as compared to people without diabetes, but the effects of VCAM-1 depletion on the renal macrophage infiltration have not been studied to our knowledge." (PMID 34199409, 2021). "In a diabetes-accelerated atherosclerotic model, the H2S donor GYY4137 reduced plaque formation, NLRP3 inflammasome activation, and the expression of both intercellular cell adhesion molecule 1 (ICAM1) and vascular cell adhesion molecule 1 (VCAM1)." (PMID 33374506, 2020). "VCAM1 was not significantly correlated with BMI (p = 0.71) but was elevated in participants with diabetes mellitus by 61 ng/ml (95% CI: 28, 95, p < 0.01)." (PMID 28673336, 2017).
diabetes (continued). "In the present study it was found that the expression levels of VCAM-1 in the aortic tissues were increased in patients with smoking habits, diabetes mellitus or hypertension, compared with the subjects without these risk factors." (PMID 26622332, 2015). "In fact, RBP4 stimulates human primary endothelial cells to produce pro-inflammatory molecules such as vascular cell adhesion molecule 1 (VCAM1), CCL2, and IL-6 resulting in the progression of endothelial inflammation in cardiovascular disease and microvascular complication in diabetes." (PMID 23781214, 2013). "Effect of diabetes on ICAM-1 and VCAM-1 was significantly blocked by baicalein." (PMID 23437353, 2013). "Another conclusion from the present study is that measurements of vascular endothelial markers by RT-PCR using total retinal RNA have limited resolution and are not sensitive enough to dissect e.g. the effects of diabetes or genotype on VCAM-1 expression." (PMID 20856927, 2010). "As well, pioglitazonereduces the levels of ICAM-1 and VCAM-1 in obese patients without diabetes, without affecting soluble E-selectin levels." (PMID 19107216, 2008). "In contrast, the chemokine RANTES or the adhesion molecules ICAM-1 and VCAM-1 were not transcriptionally regulated in the kidney in response to hypertension or diabetes." (PMID 15918915, 2005). "Furthermore, CTRP3 inhibits HGHL-induced VCAM-1 expression in an AMPK-dependent manner in HRMECs, suggesting the novel therapeutic potential of CTRP3 for the treatment of DR, a serious and widespread complication of diabetes." (PMID 28632765, 2017). "The concept that sRAGE levels may be elevated in response to serum AGE levels and reflect tissue RAGE expression in diabetes is supported by similar elevations in levels of ICAM-1 and VCAM-1 under the same circumstances since RAGE belongs to the same immunoglobulin superfamily as ICAM-1 and VCAM-1." (PMID 27434539, 2016). "Already after 4 weeks of diabetes, a time-point when no changes in aortic plaque size had yet occurred, expression of VCAM-1, MCP-1, IL-1β, Cox2, TF and maybe also IL-6 and ICAM-1 (borderline significance) were higher than in control non-diabetic mice." (PMID 23755169, 2014). "Moreover, our data indicate disruption and relocation of VE-cadherin with a concomitant increase in the soluble VCAM-1 expression, by hypo and hyperglycemia in hCMEC/D3 cells, effects that are critical to progression of BBB inflammation and augmented leukocyte infiltration in diabetes." (PMID 24708805, 2014). "However, when mRNA levels of VCAM-1, ICAM-1 and E-selectin were studied in isolated retinal vessels from ApoE−/− using the same assays as for intact retina, a clear increase of ICAM-1 in response to diabetes was observed (p<0.05) and similar trends were seen for VCAM-1 and E-selectin (n.s.)." (PMID 20856927, 2010). "Diabetes significantly increased the retinal expression of phospho-ERK1/2, HMGB1, VCAM-1, and ICAM-1 in comparison with the retinal levels in nondiabetic control rats." (PMID 39851513, 2025). "Although there were correlations between cognitive performance and various cognitive scores, IL‐6, MDA, NSE, VCAM‐1, and TNF‐α did not play a mediator role in the neuropathology of diabetes‐related cognitive impairment." (PMID 39829127, 2025). "In this study, markers of endothelial dysfunction such as the ratios of VEGF/sVEGF, ICAM-1 and VCAM-1 were increased in patients with FTD and diabetes in comparison with those of patients without DM." (PMID 39202319, 2024). "There were beneficial effects on VCAM-1 in people with chronic renal failure and on the homeostatic model assessment of insulin resistance and LDL-cholesterol in people without diabetes." (PMID 29232895, 2017).
diabetes (continued). "The rise of ICAM-1 and VCAM-1 in vasculopathy and their negative correlation with A/BI support the role of inflammation in pathogenesis of diabetic PVD and indicates that inflammation could be the cause of reduced vascular integrity and contribute to vascular complications in diabetes." (PMID 25287126, 2014). "Lack of TNFα increased higher basal VCAM-1 protein and sVCAM-1, but failed to up-regulate IL-6 and IL-1β mRNA and VCAM-1 protein in response to diabetes." (PMID 20856927, 2010). "Although there were correlations between cognitive performance and various cognitive scores, mediator analysis results indicated that the biomarkers IL‐6, MDA, NSE, VCAM‐1, and TNF‐α did not play a mediating role in the neuropathology of diabetes‐related cognitive impairment." (PMID 39829127, 2025). "Further adjustment for height, body mass index, systolic blood pressure, antihypertension therapy, diabetes status, current smoker, current alcohol use, and total and HDL cholesterol did not appreciably change point estimates for MMP-2, TIMP-2, VCAM-1, or SLPI." (PMID 34521347, 2021). "AM was not a predictor, while b-FG, VCAM-1 and ICAM-1 could be predictors for peripheral blood flow in diabetic PVD." (PMID 25287126, 2014).
Sepsis (113 papers, 2009 to 2026). Sepsis is defined as life-threatening organ dysfunction caused by a dysregulated host response to infection. "Elevated levels of soluble intercellular adhesion molecule-1 (ICAM-1) and soluble vascular cell adhesion molecule-1 (VCAM-1) have been observed in patients with sepsis and are associated with worse clinical outcomes." (PMID 39821561, 2025). "First, Multiple Organ Dysfunction and even death have been reported to be associated with increased levels of VCAM-1 in adults and neonates diagnosed with sepsis." (PMID 36969221, 2023). "Endothelial E-selectin and VCAM-1 expression promotes leukocyte adhesion, and high leukocyte infiltration in various organs is associated with a poor prognosis in sepsis patients." (PMID 36544136, 2022). "New diagnostic biomarkers of sepsis were screened by iTRAQ2D‐LC MS/MS, and proteins of ApoC3, VCAM1, B2M, and ApoE provide a supplement to classical biomarkers for septic diagnosis." (PMID 34825737, 2022). "Both intercellular adhesion molecule-1 (ICAM-1) and vascular cell adhesion molecule-1 (VCAM-1) have been implicated in the migration of neutrophils during sepsis-induced ALI." (PMID 34074039, 2021). "In conclusion, we have demonstrated here for the first time that CD34+/CD133+-stem cells in the clinical setting of sepsis exhibit a high expression of VCAM-1 and that this expression is associated with patient survival." (PMID 29601599, 2018). "Logistic regression analysis revealed an inverse association between expression of VCAM-1 and survival probability in the sepsis group (p = 0.05)." (PMID 29601599, 2018). "Collectively, the anti-inflammatory effects of cilastatin reduced the hyperinflammatory state associated with sepsis, leading to decreased expression of endothelial adhesion molecules (VCAM-1, ICAM-1), reduced chemokine production, and lowered leukocyte infiltration in the kidney." (PMID 40869248, 2025). "Finally, we selected six DEPs that were closely associated with sepsis: cathepsin B (CatB), vascular endothelial cell adhesion molecule (VCAM-1), neutrophil gelatinase-associated lipoprotein (NGAL), protein S100-A9, prosaposin, and thrombospondin-1 (TSP-1)." (PMID 39049003, 2024). "Among these, VCAM-1 was significantly associated with sepsis mortality." (PMID 29601599, 2018). "In this study, we demonstrate that CD34+/CD133+-stem cells, which have been described to be rich in vascular progenitor cells, exhibited a high expression of the adhesion molecule VCAM-1 in septic patients, which revealed a positive association with sepsis mortality." (PMID 29601599, 2018). "Consistent with the increased H3K14la levels, expression levels of both VCAM‐1 and TF, two biomarkers of EC activation, were decreased by 2DG and oxamate pretreatment, indicating the alleviation of sepsis‐induced pulmonary EC activation." (PMID 39822760, 2025). "Upon the onset of sepsis, activated ECs orchestrate the infiltration of leukocytes by adhesion molecules such as vascular adhesion molecule‐1 (VCAM‐1), leading to lung injury via the release of proteases and oxygen‐derived radicals." (PMID 39822760, 2025). "Using a sepsis mouse model, they demonstrated that IL-35 suppresses VCAM-1 expression via the IL-12Rβ2:gp130 heterodimeric receptor and inhibits the MAPK-AP-1 signaling pathway." (PMID 39974277, 2025). "For example, elevated VCAM-1 increases the risks of sepsis, septic shock, multiple-organ dysfunction syndrome, and death." (PMID 40006998, 2025). "During sepsis, endothelial cell-derived EVs (EC-EVs) with heightened levels of vascular cell adhesion molecule 1 (VCAM1) stimulate the NF-κB pathway upon binding to integrin subunit alpha 4 (ITGA4) receptors on monocytes." (PMID 39967672, 2025). "The mRNA levels of Vcam1 showed a minor increase at 4 h after CLP-induced sepsis started, compared to sham mice." (PMID 39200137, 2024).
Sepsis (continued). "In parallel, increased serum levels of VCAM-1 were described in COVID-19 patients with distinct severity under dexamethasone treatment in correlation with classic sepsis biomarkers soluble urokinase-type plasminogen activator receptor and presepsin." (PMID 38276214, 2024). "Serum levels of adhesion molecules, including E-selectin, P-selectin, intercellular adhesion molecule-1 (ICAM-1), and vascular cell adhesion molecule-1 (VCAM-1), have been observed to correlate with sepsis severity, number of organ failures, and mortality." (PMID 39063011, 2024). "Consistent with the result obtained for the whole population, the HDL-C concentration correlated positively with the VCAM-1 mRNA fold change in the sepsis group (r = 0.370, p = 0.0007)." (PMID 38603717, 2024). "In patients with sepsis, increased ICAM-1 and VCAM-1 levels have been associated with organ dysfunction and mortality." (PMID 39409009, 2024). "Pro-inflammatory cytokines, mainly TNF-α, upregulate the expression of both ICAM-1 and VCAM-1, and these adhesion molecules are highly expressed in endothelial cells during sepsis." (PMID 38254684, 2024). "Univariable and multivariable logistic regression for the association between apoB-depleted plasma’s anti-inflammatory capacity (represented by VCAM-1 mRNA fold change value) and the presence of sepsis (n = 130)." (PMID 38603717, 2024). "Our study showed increased ICAM-1 and VCAM-1 immunoreactivity in co-localization with LYVE-1 in a sepsis model." (PMID 37686458, 2023). "Studies in animal models have demonstrated that endothelial ICAM-1 expression is upregulated during sepsis, and there is also a transient increase in VCAM-1." (PMID 37048076, 2023). "Endothelial activation in sepsis leads to the expression of E- and P-selectin, VCAM-1, and ICAM-1 on the endothelial cell surface, which in turn causes leukocytes to roll, adhere, and transmigrate across the endothelial cells." (PMID 37700349, 2023). "The pooled mean concentration of VCAM-1 was significantly higher in patients with SAE compared to the patients with sepsis alone (SMD 0.55; 95% CI 0.12–0.98; p = 0.01)." (PMID 36802387, 2023). "In sepsis, endothelial cells express inflammatory cell-related adhesion molecules such as P-selectin, E-selectin, vascular cell adhesion molecule 1 (VCAM1), and intercellular adhesion molecule 1 (ICAM1)." (PMID 36769749, 2023). "Immunohistochemistry revealed that echinacoside alleviated the upregulation of VCAM-1 expression in endothelial cells induced by sepsis." (PMID 38001778, 2023). "As sepsis advances, VCAM-1 and ICAM-1, which are expressed in large quantities on the activated EC surface of septic patients, are also cleaved and released into the circulation." (PMID 38259971, 2023). "In this study, the three adhesion-related factors (CD62L, CD62E and VCAM-1) of patients with S-AKI were higher than those with sepsis." (PMID 36333626, 2023). "In contrast, other research has reported that the ICAM-1 and VCAM-1 levels correlated significantly with organ dysfunction and mortality in patients with sepsis." (PMID 36333626, 2023). "Our study suggests that the glycosaminoglycan heparan sulfate and the glycoproteins ICAM-1, VCAM-1, and E-selectin are significantly increased in the plasma of sepsis patients with cognitive impairment." (PMID 36802387, 2023). "This suggested there was increased expression of ICAM-1 and VCAM-1 predominantly on liver sinusoidal endothelial cells and pulmonary endothelial cells, respectively, during sepsis." (PMID 37686458, 2023). "Compared with the sepsis serum group, the mRNA levels of VCAM-1 (1.00 ± 0.03 vs. 0.36 ± 0.01, p < 0.05) and ICAM-1 (1.00 ± 0.06 vs. 0.37 ± 0.01, p < 0.05) were significantly reduced after treatment with M8I." (PMID 35145983, 2022). "Adhered PBMCs and PMNs were significantly increased in sepsis serum mixed medium compared to the control, similar to the mRNA and protein levels of VCAM-1 and ICAM-1." (PMID 35145983, 2022).